ICAM1 (intercellular adhesion molecule 1)
Diseases named in the same sentence as ICAM1 in open-access papers (continued):
Sharing a sentence is not in itself a finding about the gene and the disease.
ZIKV infection (6 papers, 2019 to 2022). "Significant increase in the gene expression of various laminin alpha-chains as well as fibril forming collagen chains was seen in ZIKV-infected TEC, as well as higher levels of VCAM1 and ICAM-1 expression in TEC after ZIKV infection." (PMID 31992777, 2020). "Interestingly VCAM1 and ICAM1, encoding two cell adhesion molecules (CAMs) involved in leukocyte docking to the BBB, were also upregulated upon ZIKV infection." (PMID 32753493, 2020). "ICAM1 and VCAM1 are involved in immune cell migration across the blood–brain barrier, where an increase in immune cells in the brain might contribute to the neuropathogenesis associated with intrauterine ZIKV infection." (PMID 32380717, 2020). "We observed that ZIKV infection led to selective upregulation of CAMs (VCAM1, ICAM1, and SELE) whereas PECAM was downregulated upon ZIKV AF infection (≤2-fold, P value ≤ 0.05 compared to CT), confirming the data obtained previously with the array." (PMID 32753493, 2020). "In this context, ICAM-1 and VCAM appeared as a main hub connecting distinct clusters of genes whose expression was altered secondary to ZIKV infection." (PMID 31992777, 2020). "HSPG2 and ICAM-1 mRNA expression increased during culture of hSCs, but this was not affected by ZIKV infection." (PMID 31289325, 2019). "The intercellular cell adhesion molecule (ICAM-1) a cell surface receptor that can be up regulated by IFNγ, IL1β and TNFα in SCs51 showed increased mRNA expression during culture but was not modulated by ZIKV infection." (PMID 31289325, 2019).
acute GVHD (5 papers, 2014 to 2022). "Elevated D28 ST2 and D14 ICAM1 levels associated significantly with acute GVHD in this study thus explaining the possible prognostic value of these biomarkers in HSCT." (PMID 32885223, 2020). "The ROC analysis also demonstrated significant association of D14 ICAM1 and D28 ST2 with acute GVHD (AUC of 0.6 and 0.65, respectively)." (PMID 32885223, 2020). "In mouse models of acute GVHD, allogeneic recipients showed upregulation of VCAM-1, ICAM-1 in the GI tract compared to syngeneic recipients with concomitant increase in T cell infiltration in GVHD target organs of skin, liver and GI tract." (PMID 36505438, 2022). "D14 ICAM1 and D28 ST2 levels were significantly elevated in patients who developed acute GVHD (all grades) when compared to those without GVHD." (PMID 32885223, 2020). "Similarly, in patients who developed acute GVHD (all grades included), D28 ST2, and REG3α as well as D14 ICAM1 were significantly higher compared to those without GVHD." (PMID 32885223, 2020).
acute lymphoblastic leukemia (5 papers, 2012 to 2025). Leukemia with an acute onset, characterized by the presence of lymphoblasts in the bone marrow and the peripheral blood. "Upon chemotherapy treatment for T-cell Acute Lymphoblastic Leukemia (T-ALL), T-ALL cells export mitochondria to MSCs via TNTs in an ICAM-1–mediated manner, reducing intracellular ROS and promotes chemoresistance: blocking TNTs formation or adhesion abolishes MSC-induced protection." (PMID 41226616, 2025). "Also, CCL2, ICAM1 and VCAM1 have a positive effect on MSCs adhesiveness, survival and proliferation in patients with acute lymphoblastic leukaemia." (PMID 29495420, 2018). "CD54, also known as intercellular adhesion molecule (ICAM)-1, is expressed in hematologic malignancies, including acute lymphoblastic leukemia (ALL), and plays a role in the homing of malignant plasma cells to the BM." (PMID 23251606, 2012).
ankylosing spondylitis (5 papers, 2014 to 2026). An autoimmune chronic inflammatory disorder characterized by inflammation in the vertebral joints of the spine and sacroiliac joints. "Of note, a previous study in patients with ankylosing spondylitis showed that a cycle of 10 whole-body cryotherapy procedures with subsequent kinesiotherapy reduced plasma ICAM-1 levels as compared to kinesiotherapy alone, suggesting a positive effect on EA." (PMID 35488311, 2022).
Arterial thrombosis (5 papers, 2020 to 2025). The formation of a blood clot inside an artery. "EC autophagy deficiency improves the levels of vascular cell adhesion molecule-1 (VCAM-1), intercellular adhesion molecule-1 (ICAM-1), von Willebrand factor, and P-selectin, thus promoting the infiltration of macrophages and foam cells, as well as increasing the risk of arterial thrombosis." (PMID 35096837, 2021). "Streptococcus receptor polysaccharides may stimulate aortic endothelial cells, and cytokines (IL-6, IL-8, and monocyte chemoattractant protein-1) and intercellular adhesion molecule-1 showed increased expression, thus contributing to cardiovascular disease progression and arterial thrombosis." (PMID 40822584, 2025).
autoimmune thyroid disease (5 papers, 2013 to 2025). Inflammatory disease of the thyroid gland due to autoimmune responses leading to lymphocytic infiltration of the gland. "Second, elevated iodine intake upregulates the expression of intercellular adhesion molecule-1 on thyroid cells, facilitating monocyte infiltration and ensuing inflammation, a finding corroborated by mouse models of autoimmune thyroiditis." (PMID 39583966, 2024). "Intercellular adhesion molecule-1 (ICAM-1) and major histocompatibility complex (MHC) II molecules are thought to be causative factors in autoimmune thyroid disease (AITD), and their expression can be suppressed by TSH." (PMID 37602950, 2023). "Increased ROS levels and oxidative stress also contributes to the development of thyroid autoimmune diseases through fragmentation of thyroglobulin and increased expression of intercellular adhesion molecule 1 (ICAM-1) by thyrocytes." (PMID 33767633, 2021). "A research investigation revealed that autoimmune-mediated dysthyroidism is linked to elevated levels of vascular cell adhesion molecule 1 (VCAM-1), intercellular adhesion molecule-1 (ICAM-1), and TIMP-1 in peripheral blood when compared to cases of non-autoimmune thyroid disease." (PMID 40095713, 2025).
babesiosis (5 papers, 2017 to 2025). Babesiosis refers to a condition caused by microscopic parasites that infect the red blood cells. "Nuclear factor kappa-light-chain-enhancer of activated B cells (NF-κB) activation drives the release of pro-inflammatory molecules, such as IL-6, TNF-alpha, ICAM-1, and IL-8, previously associated with babesiosis." (PMID 40305281, 2025). "Babesiosis disrupts the delicate balance between apoptosis and inflammation, ICAM-1, a cell adhesion molecule, facilitates the interaction between leukocytes, immune cells, and endothelial cells, which line the blood vessels." (PMID 38784653, 2024). "Dogs with babesiosis also had increased concentrations of TM, ICAM-1 and HMGB-1 and decreased plasminogen and PAI-1 at presentation compared to day 6 after treatment." (PMID 28363279, 2017).
bipolar disorder (5 papers, 2019 to 2024). A disorder of the brain that causes unusual shifts in mood, energy, activity levels and the ability to carry out day-to-day tasks. "We also found increased CD163, CD14 and ICAM1 mRNAs in high compared to low inflammation bipolar disorder (39–104%, all post hocp ≤ 0.008)." (PMID 34911938, 2021). "Studies report contrasting results on imbalances in adhesion molecules, such as ICAM-1 and VCAM-1, in patients with both bipolar disorder and MDD, with the majority of them indicating a potential link between immune dysregulation and the development and progression of these conditions." (PMID 39056795, 2024).
bronchiectasis (5 papers, 2015 to 2025). Segmental, irreversible dilation of the bronchial tree resulting in the accumulation of secretions which leads to obstruction. "In this study, immunohistochemical staining of stable IPF cases demonstrated a higher degree of ICAM-1 staining in the honeycomb lung or epithelial cells of bronchiectasis than in interstitial cells." (PMID 26543791, 2015). "In healthy tissue, ICAM-1 was rarely expressed; however, in patients with stable IPF, ICAM-1 was observed, particularly, in the epithelial cells of cysts and bronchiectasis." (PMID 26543791, 2015). "In general, we speculate that the curative mechanisms of BMGLF in bronchiectasis are primarily associated with the expressional regulation of inflammatory factors such as IL6, IL10, MMP9, CXCL8, MAPK1, and ICAM1." (PMID 33488758, 2021). "Bacterial load in non-CF bronchiectasis has been correlated with increases in airway (NE, IL-8, IL-1β and TNF-α) and systemic (ICAM-1, E-selectin) derived inflammatory markers, phenomena confirmed in vitro using bronchial epithelial cell lines treated with sputum from bronchiectasis patients." (PMID 29788954, 2018).
cardiomyopathy (5 papers, 2011 to 2023). A disease of the heart muscle or myocardium proper. "Taken together, these findings implicate that Tat-mediated induction of ICAM-1 expression plays a critical role in monocyte adhesion observed in HIV-1-associated cardiomyopathies." (PMID 23555914, 2013). "Reduction of VCAM-1 and intercellular adhesion molecule 1 (ICAM-1) by CBD treatment has also been reported in an animal model of diabetes-induced cardiomyopathy, high glucose-induced endothelial cell barrier disruption, and in TNF-α exposed sinusoidal epithelial cell assays." (PMID 36109476, 2023).
chronic lymphocytic leukemia (5 papers, 2017 to 2022). "In chronic lymphocytic leukemia cells, ephrin-A4 activation by EphA2-Fc significantly reduced cell adhesion to fibronectin-, collagen-, laminin-, ICAM-1-, and VCAM-1-coated surfaces." (PMID 28851287, 2017). "Interestingly, RNAi-mediated ablation of BCL3 (B-cell CLL/Lymphoma 3) expression in activated fibroblasts, leads to a strong decrease of ICAM-1 expression both in LIF-activated fibroblasts and in CAF (data not shown)." (PMID 27901489, 2017). "The same approach was utilized in healthy B-lymphocytes compared to chronic lymphocytic leukemia cells (CLL) where PTPRG activation was found to inhibit adhesion by preventing the LFA-1 high-affinity state transition induced by CXCL12 or BCR necessary to bind on both ICAM-1 and VCAM1." (PMID 35053232, 2022).
Cirrhosis (5 papers, 2011 to 2025). A chronic disorder of the liver in which liver tissue becomes scarred and is partially replaced by regenerative nodules and fibrotic tissue resulting in loss of liver function. "Parameters associated with increased HCC incidence were cirrhosis, hepatic decompensation, and soluble serum intercellular adhesion molecule 1 (sICAM-1) MFI." (PMID 28894136, 2017). "A study in China associated SNPs at codons R241-E469 of the intercellular adhesion molecule-1 (ICAM-1) gene with decompensated cirrhosis." (PMID 37764954, 2023). "Cirrhotic rats had significantly higher levels of proinflammatory cytokines including TNF-α, IL-1β and IL-6, and soluble ICAM-1, which have been shown to play important roles in development of cirrhosis." (PMID 22022478, 2011).
clear cell renal cell carcinoma (5 papers, 2018 to 2026). "An ICAM1 mutation is most often seen in ovarian epithelial tumors, whereas it is least frequently found in renal clear cell carcinoma." (PMID 37671167, 2023). "For example, in renal clear cell carcinoma, RARRES1 plays an anti-tumor role by promoting ICAM1 expression and inducing the activation of M1 macrophages." (PMID 40002669, 2025).
diffuse large B-cell lymphoma (5 papers, 2020 to 2023). "Here we studied the expression level of ICAM-1 in 102 diffuse large B-cell lymphoma patients and investigated its association with rituximab treated progression-free survival (PFS) and overall survival (OS)." (PMID 33288735, 2020). "These included CD40, TRAF1, EBI3, and ICAM1, which were previously established as TES1 target genes in studies of cell lines overexpressing LMP1, including BL-41 Burkitt and BJAB diffuse large B-cell lymphoma models." (PMID 38009935, 2023).
encephalitis (5 papers, 2019 to 2024). An acute inflammatory process affecting the brain parenchyma. "Low grade encephalitis in ICAM-1 -/- mice is associated with down-regulation of proinflammatory cytokines and differential regulation of anti-inflammatory genes in the brain tissue compared to infection in the wild-type mice." (PMID 30781656, 2019). "Significant methylation alterations were found in the promoters of CSF3, CCL2, and ICAM1 in LGI1 encephalitis patients comparable to healthy individuals." (PMID 37644514, 2023). "Such BDNF-loaded exosomes crosses BBB via intercellular adhesion molecule 1 (ICAM-1) which is upregulated under encephalitis-related inflammation." (PMID 38139999, 2023). "Decreased PDCD1 with increased ICAM1 could predict unfavorable prognosis in one-year follow-up for LGI1 encephalitis patients." (PMID 37644514, 2023). "The ROC curve also indicated that the combination of PDCD1 and ICAM1 could predict unfavorable prognosis of LGI1 encephalitis patients at one-year follow-up more accurately than either PDCD1 or ICAM1 alone (AUC = 0.936 p = 0.003 vs. AUC = 0.821 p = 0.028; AUC = 0.778 p = 0.052)." (PMID 37644514, 2023). "Mice that lack a functional ICAM-1 have a less leaky BBB and exhibit marked reduction in encephalitis following infection with V3000." (PMID 30781656, 2019).
esophageal cancer (5 papers, 2015 to 2024). A primary or metastatic malignant neoplasm involving the esophagus. "In this study, ICAM1 was identified to express in higher stemness properties of esophageal cancer CE146T cells using a comparative proteomic approach." (PMID 26571024, 2015). "The metabolism gene signature, consisting of four shared metabolic hub genes (i.e., FA2H, ICAM1, F3, and CYBA), was further identified to be remarkably elevated in TCGA esophageal cancer tissues compared with combined normal tissues from both TCGA and GTEx dataset." (PMID 36274060, 2022).
experimental autoimmune encephalomyelitis (5 papers, 2011 to 2023). An autoimmune demyelinating disease of the central nervous system that is produced experimentally in animals by the injection of homogenized brain or spinal cord in Freund's adjuvant. "However, somewhat paradoxically, in earlier studies, IFN-β was shown in murine models of experimental autoimmune encephalomyelitis (EAE) to decrease the abundance of adhesion molecules on brain capillaries such as ICAM-1 and VCAM-1." (PMID 37239045, 2023). "Ultrastructural studies in an experimental autoimmune encephalomyelitis model revealed polar localization of ICAM-1, VCAM-1, and MAdCAM-1 on the apical surface of choroid plexus epithelial cells and their complete absence on the fenestrated endothelial cells within the choroid plexus parenchyma." (PMID 21592385, 2011).
gastric tumors (5 papers, 2014 to 2025). "Meanwhile, mRNA levels of NF-kB downstream metastasis-related genes including Vimentin, MMP-2, MMP-9, VEGF, ICAM-1 and VCAM-1 were significantly enhanced in the primary gastric tumors." (PMID 30728051, 2019). "Additionally, CAR-T cells directed against intercellular adhesion molecule 1 (ICAM-1) have exhibited substantial therapeutic efficacy against both primary and metastatic gastric tumors." (PMID 40028336, 2025). "Furthermore, expression of mRNA transcripts for the bona fide STAT3‐target genes Socs3, Icam1, and Reg3a, which are both induced by IL11 in gastric tumors, were significantly decreased in tumors from bazedoxifene‐treated animals." (PMID 30885958, 2019).
gestational diabetes (5 papers, 2016 to 2025). Carbohydrate intolerance first diagnosed during pregnancy. "Several cytokines including leptin were associated with maternal body weight (coeff 0.9; p = 2.31 × 10−5), smoking habits (i.e., ICAM-1 coeff 133.3; p = 0.09), or gestational diabetes (i.e., ICAM-1 coeff 688; p = 0.06)." (PMID 37299395, 2023). "In addition, the GSK3 inhibitor CHIR99021 reduces ICAM-1 expression in adipose tissue and skeletal muscle of gestational diabetes." (PMID 30585203, 2018). "Thus, the aim of this study was to analyse the serum levels of ADMA and s-ICAM-1 as the markers of endothelium dysfunction in patients with gestational diabetes." (PMID 26981539, 2016).
hemorrhage (5 papers, 2011 to 2016). Loss of blood from the vascular compartment to the exterior or into nonvascular body space as a result of rupture or severance of the blood vessels. "From this study, maraviroc activated hepatic PPARγ and decreased hepatic ICAM-1 and IL-6 levels and neutrophil activity following trauma-hemorrhage." (PMID 24205332, 2013). "Tissue MPO activity is an indicator of neutrophil infiltration, and it has been correlated with ICAM-1 expression after trauma-hemorrhage." (PMID 23755293, 2013). "The effects of these treatments were then examined with respect to hepatic injury as well as hepatic myeloperoxidase (MPO) activity, intercellular adhesion molecule-1 (ICAM-1), interleukin-6 (IL-6), and PPARγ levels following trauma-hemorrhage." (PMID 24205332, 2013). "MPO activity is an indicator of neutrophil activation, and it has been correlated with tissue ICAM-1 expression after trauma-hemorrhage." (PMID 24205332, 2013). "Trauma-hemorrhage significantly increased ICAM-1 concentrations in the liver (4546.0±312.5 vs. 807.5±133.2 pg/mg protein, p<0.05)." (PMID 23755293, 2013). "Treatment with maraviroc attenuated the trauma-hemorrhage-induced increase in ICAM-1 concentrations." (PMID 24205332, 2013). "Intercellular adhesion molecule (ICAM)-1 is enhances a firm adhesion of neutrophils to the vascular endothelium, and markedly up-regulated following trauma-hemorrhage." (PMID 23755293, 2013). "Intercellular adhesion molecule-1 (ICAM-1) is up-regulated after trauma-hemorrhage, and it enhances a firm adhesion of neutrophils to the vascular endothelium." (PMID 23285267, 2012). "In this study, our results indicate that trauma-hemorrhage results in a significant increase in hepatic pro-inflammatory cytokine/chemokine levels and ICAM-1 expression, which are accompanied with increased hepatic MPO activity." (PMID 22022464, 2011). "The intercellular adhesion molecule (ICAM)-1 enhances firm adhesion of neutrophils to the vascular endothelium and is markedly up-regulated after trauma-hemorrhage." (PMID 22022464, 2011). "The effects of these treatments were then examined with respect to hepatic injury as well as hepatic myeloperoxidase (MPO) activity, ICAM-1, IL-6, and phospho (p)-p38 MAPK/p38 MAPK levels following trauma-hemorrhage." (PMID 23755293, 2013).
hyperuricemia (5 papers, 2013 to 2024). An abnormally high level of uric acid. "In this study, we evaluated the therapeutic potential of WPP and CPP in the treatment of hyperuricaemia by measuring XO activity inhibition, the levels of UA, Cr and UN in serum and urine and the expression of ICAM-1, IL-1β and IL-6, and by observing kidney histological damage." (PMID 35087407, 2021). "We examined the expression of frequently reported main ligands and found a significant upregulation of ICAM‐1 and fibronectin, which indicated potential role of ITGAM in cell–ECM and cell–cell interactions in kidneys of hyperuricemia‐related CKD." (PMID 38911067, 2024). "The production of IL-1β, IL-6 and ICAM-1 was also decreased in the WPP-treated group and CPP-treated group to inhibit the inflammatory process in hyperuricaemia." (PMID 35087407, 2021). "The ICAM-1, IL-1β and IL-6 levels were measured to evaluate the anti-inflammatory effects of WPP and CPP on the treatment of hyperuricaemia." (PMID 35087407, 2021). "In this study we also found that hyperuricemia induced increased inflammation mediators such as MCP-1 and ICAM-1." (PMID 29089036, 2017).
infarction (5 papers, 2017 to 2025). A localised pathological necrosis of tissue resulting from obstruction of the blood supply usually by a thrombus, an embolus, or vascular torsion. "Moreover, Icam1, a marker for leukocyte recruitment, was actively induced after infarction." (PMID 29342151, 2018).